BRCA1 (BRCA1 DNA repair associated)
Diseases named in the same sentence as BRCA1 in open-access papers (continued):
Sharing a sentence is not in itself a finding about the gene and the disease.
breast cancer (continued). "In addition, we demonstrated that AZD2281 induces growth inhibition in BRCA wild-type breast cancer cell lines with BRCA1 allelic loss, indicating that breast cancer patients with BRCA1 allelic loss may benefit from PARP inhibitors." (PMID 25975349, 2015). "Moreover, it is believed that BRCA1 mutation accounts for the progress of hereditary breast cancers and is in connection with unique clinicopathological characteristics compared with sporadic breast cancers." (PMID 25695063, 2015). "The identification of target genes and pathways affected by deregulated miRNAs in BRCA1/2-associated breast carcinomas is important for attaining a better understanding of BRCA1/2-specific breast tumorigenesis and could yield new diagnostic biomarkers and therapeutic targets." (PMID 26378051, 2015). "In this model, the predisposition in BRCA1 has the highest frequency in the familial breast cancer population, other known predispositions gradually decrease their frequencies to insignificant levels, and the predispositions for many BRCAx familial breast cancers are family-specific." (PMID 24969172, 2014). "Thus, reduction of survivin via SIRT1 activity may play an important role in BRCA1-associated mammary tumor formation." (PMID 25486244, 2014). "A recently opened study is recruiting unaffected BRCA1/2 mutation carriers to explore any relationship between TL (plus a variety of metabolic and lifestyle factors) and breast cancer risk, and will avoid the compounding factors such as treatment effects which may bias the retrospective studies." (PMID 24489760, 2014). "This is in concordance with the fact that constitutional methylation is mono allelic, hence only one allele of the BRCA1 gene is methylated in the carriers, however, in the breast cancer patients, the two alleles are affected (according to Knudsen’s hypothesis of tumor suppressor deactivation)." (PMID 25403427, 2014). "In addition to germline BRCA1/2 mutations, silencing of BRCA1/2 expression can also occur via epigenetic processes such as promoter hyper- methylation and this has been documented in 11-14% of breast cancers and 11-35% of ovarian cancer patients." (PMID 25526776, 2014). "In addition, we analyzed the correlation between DNMT1-positive cells or mRNA levels and the number of methylated sites within the E2F1 motif (+182) or DNMT1 core promoter region (-99 to +521) in BRCA1-mutated breast cancer and adjacent normal breast tissue (Figure2Ei-Eiv)." (PMID 24502362, 2014). "Interestingly, a similar result was reported in the Israeli study, where BRCA1/2 mutation carriers, a large majority of them already diagnosed with breast cancer, demonstrated only in 24.8% low FMR1 alleles, while random controls demonstrated low FMR1 alleles in 31.5% of women." (PMID 25036526, 2014). "For example, for a woman diagnosed with breast cancer at 50 years or older, the LR in favor of positive BRCA1 mutation status would be 3.5 if her tumor were known to be ER negative but grade status was unknown, and 2.4 if reported as grade 3 without information on ER status." (PMID 25857409, 2014). "Therefore, it is likely that focusing on the NHEJ repair pathway may lead to the identification of additional susceptibility loci related to non-BRCA1/2 breast cancer." (PMID 25360583, 2014). "In addition, emerging evidence has suggested that: (i) both genetic and environmental factors contribute to impaired GR function; (ii) GR inactivation is a hallmark for BRCA1-mutated breast cancer tissues; and (iii) the BRCA1-interacting protein NELF-B participates in GR-mediated gene induction." (PMID 24629067, 2014).
breast cancer (continued). "We hypothesized that the aCGH patterns resembling BRCA1- or 2-mutated breast cancers (BRCA-likeCGH status) would identify a subgroup of not only TN, but also ER-positive, HER2-negative breast cancer patients with tumors exquisitely sensitive to DNA DSB-inducing agents." (PMID 24887359, 2014). "Nevertheless, an extensive evaluation of the prevalence of the BRCA1 mutation in TN and HR(−) tumors similar to that performed in the British population is needed for proper genetic counseling of individuals and families at higher risk of breast cancer in Brazil." (PMID 23469205, 2013). "Furthermore BRCA1/2 mutation is rare in cases of sporadic breast cancer." (PMID 23738139, 2013). "Similarly, the breast cancer risk by age 40 is predicted to be 4–9% for the 5% of BRCA1 carriers at lowest risk compared to 20–49% for the 5% at highest risk, whereas the ovarian cancer risk at age 50 ranges from 3–7% for the 5% at lowest risk and from 18–47% for the 5% at highest risk." (PMID 23544013, 2013). "This study combined a functional BRCA1 assay and structural analyses to predict whether specific missense variants in the BRCA1 C-terminal region have pathological significance, contributing to breast cancer risk." (PMID 23613828, 2013). "In particular, the BRCA1 gene, when harboring germline mutations, confers a high susceptibility to breast and ovarian cancer predisposition and may account for a total of 10% of breast cancer incidence." (PMID 24179442, 2013). "The Ashkenazi Jewish population has been reported to have higher rates of breast cancer compared with other Caucasian populations, which may be at least partially explained by its high prevalence of two founder mutations in BRCA1 and one founder mutation in BRCA2." (PMID 23668689, 2013). "Interestingly, a significant proportion of TNBC show high expression of miR-155 (moreover, it was shown to be epigenetically regulated by BRCA1 and up-regulated in BRCA1-deficient or BRCA-mutant breast cancer) and stimulated by pro-oncogenic stimuli such as hypoxia, both risk factors for TNBC." (PMID 24284394, 2013). "Furthermore, the proximity of this macrosatellite to the BRCA1 gene combined with its high degree of polymorphism raise the interesting possibility that it could be involved in breast cancer susceptibility." (PMID 24146815, 2013). "Thus, 10q25.3 is likely a breast cancer risk-modifying locus for BRCA1 mutation carriers." (PMID 23544013, 2013). "Application of the new pharmacological liquid DIM substance with high bioavailability (substance N3) may be considered the perspective approach of effective personalized treatment and breast cancer prevention in patients of high-risk groups, particularly in women with BRCA1 gene mutation." (PMID 24325835, 2013). "Together, these findings suggest that BRCA1 regulation of Notch signalling is important in the normal differentiation process in breast tissue, and that loss of this pathway may be a key event in the progression of basal-like breast cancers." (PMID 23863842, 2013). "Thus, an explanation for the association of adiponectin with breast cancer is that functional reduction of PPARγ signalling, leading to reduced levels of BRCA1, may impair the DNA repair mechanisms." (PMID 22701472, 2012). "Interestingly, all nine breast cancers with BRCA1 or BRCA2 mutations clustered together." (PMID 22608084, 2012). "In addition, we evaluated whether rs2180341 modifies breast cancer risk in 3,361 BRCA1 and 2,020 BRCA2 carriers from 11 centers in the Consortium of Investigators of Modifiers of BRCA1/2 (CIMBA)." (PMID 22768030, 2012). "The prevalence of BRCA1/2 in multiple organ cancer cases in our study (7.6%) was lower than previously reported (9.1%) for cases without familial history in a previous small study, which also showed 50% with BRCA1/2 mutations in cases with familial breast cancer history." (PMID 22382806, 2012).
breast cancer (continued). "In addition, our region includes cytogenetic band 4q12 which has previously been proposed as a location potentially harboring genes important in breast cancer development because of observed loss of heterozygosity at 4q12 in both BRCA1/2 and sporadic breast cancer tumors." (PMID 23190577, 2012). "Our data show that BRCA1/p220 loss of expression or function generates aggressive breast cancer cells, in part, by upregulating BRCA1-IRIS expression, implying that chemotherapeutic targeting of BRCA1-IRIS could be pursued for breast cancer patients with BRCA1/p220-associated or TN/BL diseases." (PMID 22431556, 2012). "On the other hand, there have been only a handful of studies focused on familial breast cancer, due to difficulties in collecting the tumor material, demonstrating that BRCA1/2-mutated breast tumors could be distinguished from sporadic ones based on their gene expression signatures." (PMID 22701724, 2012). "However, since BRCA1-mutation carriers are more likely to develop ER- breast tumours, there may be little rationale to support tamoxifen for the prevention of breast cancer in this population." (PMID 22312502, 2011). "Since the mutation detection rate in the families with the same number of breast cancer cases is higher in the group with earlier disease onset (Group A) than in the groups with later disease onset (Groups C and D), the age at the disease onset seems to influence the BRCA1/2 mutation detection rate." (PMID 21232165, 2011). "BRCA1 has recently been identified as a potential regulator of mammary stem/progenitor cell differentiation, and this function may explain the high prevalence of breast cancer in BRCA1 mutation carriers, as well as the downregulation of BRCA1 in a large proportion of sporadic breast cancers." (PMID 21609478, 2011). "In addition, SMAD3, like many breast cancer susceptibility genes, is in direct protein-protein interaction with BRCA1 as it counteracts BRCA1-mediated DNA repair and its MH2 domain has recently been shown to associate with BRCA1 during oxidative stress response." (PMID 21835029, 2011). "Thus, certain BRCA1 mutations that cause hyper-recombination instead of reduced DSB repair might lead to breast cancer." (PMID 21666281, 2011). "Indeed, these options have become available for the breast cancer patients with BRCA1 mutations in Latvia just recently which might explain a relatively high amount of contralateral breast cancer cases among the carriers of both BRCA1 founder mutations." (PMID 22032251, 2011). "Therefore, our data suggest that is possible to institute a pathology-based and more sensitive and specific method for prioritising women with early-onset breast cancer for BRCA1 mutation testing, similar to that which already applies to colorectal cancer and the DNA mismatch repair genes." (PMID 21343941, 2011). "For example, the risk for developing breast cancer can be estimated using mathematical models such as the Gail model, identifying the presence of pre-invasive lesions such as ductal carcinoma in situ, or detecting genetic conditions such as BRCA1 or BRCA2 mutations." (PMID 24212828, 2011). "Interestingly, loss of Brca1 associated with cellular sensitivity to gemcitabine, which unlike the taxanes and 5-FU, is not currently used among standard first lines of therapy for breast cancer." (PMID 21771338, 2011). "The observation that BRCA1 mutation carriers who are older or post-menopausal at the time of diagnosis of breast cancer are more likely to have an ER+ breast cancer may help to define a population of BRCA1 mutation carriers for whom estrogen-modifying agents will be particularly effective." (PMID 20149218, 2010).
breast cancer (continued). "In addition, developing breast cancer at a young age could indicate a genetic predisposition to the disease, particularly a mutation in the BRCA1 gene." (PMID 20380699, 2010). "To identify predictors of pathogenic mutation status in familial breast cancer patients, we explored the use of gene expression arrays to assess the effect of two DNA–damaging agents (irradiation and mitomycin C) on cellular response in relation to BRCA1 and BRCA2 mutation status." (PMID 20174566, 2010). "Interestingly, the tyrosine kinase KIT was reported to be overexpressed in basal breast cancers and BRCA1-associated basal cancers, suggesting that it may serve as a useful prognostic marker or therapeutic target." (PMID 20346151, 2010). "The poor prognosis in BRCA1 carriers may be consistent with the histological characteristics usually described for BRCA1-associated breast cancer, which show higher histologic grade and cancers that are more often hormone receptor-negative than sporadic breast cancer cases." (PMID 20219108, 2010). "Such agents may prove effective in reducing breast cancer risk amongst BRCA1 and 2 carriers." (PMID 20961453, 2010). "In fact, the available studies examining the issue of whether BRCA1/2-associated breast cancer should be treated differently from sporadically occurring, non-familial disease are almost exclusively retrospective and limited by small size and various ascertainment biases." (PMID 20877358, 2010). "The median age of affliction with breast cancer was 55 years for 185delAG in exon 2 (95% confidence interval (CI) 46.7 to 59.5), 47 years for the 4184delTCAA mutation in exon 11 (95% CI 39 to 55.4), and 41 years for exon 13 duplication (95% CI 32.9 to 49.7) of the BRCA1 gene." (PMID 19329713, 2009). "Our data show that BRCA1-deficient tumor cells are selectively dependent on EZH2 expression, and suggest that pharmacological disruption of EZH2 could provide another individualized approach for the treatment of BRCA1-mutated breast cancers, and possibly also for sporadic basal-like breast tumors." (PMID 19709408, 2009). "However, to prove the possibility of genetic susceptibility in relation to any survival difference across type of breast cancer molecular genetic studies such as BRCA1 and BRCA2 in association with survival, although the results are inconsistent, are still required." (PMID 19190627, 2009). "Slightly elevated risk of colon and prostate cancer in BRCA1 mutation carriers and increased risk of other malignancies including pancreatic, stomach and head and neck cancers and a large increase in the relative risk for male breast cancer is seen in BRCA2 mutation carriers." (PMID 19656415, 2009). "We have reported a similar finding among BRCA1 mutation carriers identified through unselected cases of breast or ovarian cancer that is, among BRCA1 carriers, the risk of breast cancer was dependent on whether the affected relative had breast or ovarian cancer." (PMID 19401704, 2009). "On these grounds, our combined selection approach could significantly reduce the number of patients who should undergo BRCA1 mutational analysis, with the possible limitation of missing one true BRCA1 mutation carrier every 100 patients selected by breast cancer familial history alone." (PMID 19818148, 2009). "In addition to the role of BRCA1 mutations in familial breast cancer, the reduced expression, or incorrect sub-cellular localization of BRCA1 protein, are postulated to be important also in the pathogenesis of sporadic breast cancer." (PMID 19695104, 2009). "In addition, basal-like tumours are a distinctive feature of BRCA1-associated breast cancers." (PMID 19165203, 2009). "Although non-BRCA1/2 risk for ovarian and breast cancers may be transmitted by different modes, a segregation analysis of 858 families of early onset breast cancer reported a residual dominantly inherited risk of breast cancer besides the risk derived from mutations in BRCA1/2." (PMID 19536330, 2009).
breast cancer (continued). "However a retrospective study demonstrated a 50% reduction in risk of contralateral breast cancer for both BRCA1 (odds ratio = 0.50: 95% CI, 0.30–0.85) and BRCA2 (odds ratio = 0.42: 95% CI, 0.17–1.02) mutation carriers who took tamoxifen after their first breast cancer." (PMID 19409108, 2009). "By careful selection of family members to be typed, i.e. early breast cancer cases distantly related to the proband and old healthy individuals nearby, segregation analysis will be a powerful tool to assess the clinical significance of unclassified variants in BRCA1 and BRCA2." (PMID 19563646, 2009). "With the BRCA1 genetic defect as a model system, underlying cross-talk between developmental signals and environmental factors may help elucidate the breast cancer risk factors in breast cancer initiation and progression." (PMID 19768112, 2009). "Next, we determined whether EZH2 is also overexpressed in human BRCA1-deficient breast cancer." (PMID 19709408, 2009). "Accumulating data indicates that BRCA1 regulates stem/progenitor cell fate in the breast, and loss of function or suppressed BRCA1 expression may lead to dysregulated stem cell self-renewal or differentiation leading to basal-type breast carcinomas." (PMID 20049202, 2009). "Therefore it is likely that a substantial proportion of the breast cancer risk in strong familial clusters with a BRCA1/2 mutation (the group of families that are usually seen by a Cancer Genetics Service), might be contributed to by modifier genes." (PMID 18513387, 2008). "However, although our study confirms that basal CKs can help to identify BRCA1 mutation carriers, this effect was weaker than previously suggested and CKs did not independently predict BRCA1 mutation either in sporadic or familial breast cancer cases." (PMID 18275599, 2008). "These considerations apply to sporadic breast cancer but may also provide insights into the mechanisms of high-penetrance susceptibility genes since risk variants at low-penetrance loci also contribute to the risk of BRCA1 and BRCA2 mutation carriers." (PMID 19094230, 2008). "Interestingly, 80–90% of hereditary breast cancers with mutations in the gene encoding BRCA1 display a basal-like phenotype, suggesting that a deficiency in the BRCA1 pathway might cause this specific phenotype." (PMID 19007432, 2008). "However, cancer-causing mutations of BRCA1 only account for 5–10% of breast cancer." (PMID 18847501, 2008). "A polygenic model with variations in several loci, each contributing a modest independent risk has been shown to best explain the residual non BRCA1/2 aggregation of breast cancer, and the effect of low penetrant genes may also at least partly explain sporadic breast cancer." (PMID 17705858, 2007). "Carboplatin, as well as other platinum derivatives, may also be good chemotherapeutic agents for basal-like breast cancers due to the implicated function of the BRCA1-pathway in this subtype because BRCA1 mutation carriers are likely to develop tumors of the basal-like phenotype." (PMID 17663798, 2007). "First-degree female relatives of breast cancer patients have an approximately two-fold increased risk over the general population, but less than 25% of this excess risk is explained by inherited mutations in known high penetrance breast cancer susceptibility genes, such as BRCA1 and BRCA2." (PMID 16685266, 2006). "We report for the first time the use of quantitative breast cancer risk assessment for use in enrollment in a breast cancer screening pilot study by combining both the established Gail model and a purely genetic model which estimates BRCA1/2 mutation risk via BRCAPRO." (PMID 16800895, 2006).